CD47 (CD47 molecule)
Diseases named in the same sentence as CD47 in open-access papers (continued):
Sharing a sentence is not in itself a finding about the gene and the disease.
tumor (continued). "Blocking the interaction of CD47 with SIRPα is able to activate phagocytic cells, including M1-like TAMs and dendritic cells (DCs), and increase tumor cells phagocytosis." (PMID 34138357, 2021). "These exosome nano-bioconjugates can release the antibodies after the selective cleavage in the acid tumor microenvironment that block the interaction between SIRPα and CD47, and thereby improve phagocytosis of macrophages." (PMID 34852849, 2021). "Numerous ongoing clinical trials and further clinical investigations will guide the tumor type, optimal combination therapy and timing of the therapy targeting the CD47/SIRPα axis." (PMID 34944850, 2021). "Mechanistically, CD47 expressed on tumor cells interacts with signal-regulatory protein-α (SIRPα) on cDCs to facilitate the recruitment of the tyrosine phosphatase SHP-1 on the phagosomal membrane." (PMID 34290401, 2021). "Given the role of macrophages in recycling iron via cellular phagocytosis, anti-CD47 immunotherapy likely effects tumor iron metabolism." (PMID 33986740, 2021). "Nath and co-authors have verified that NK Cell recruitment and activation are regulated by CD47 expression in the tumor microenvironment, which make it possible to treat cancers with CD47 mRNA targeting delivery to NK cells." (PMID 35008249, 2021). "Interest in CD47 as a regulator of anti-tumor innate immunity was heightened by reports that a CD47 blocking antibody enhances NK- and macrophage-mediated killing of tumor cells." (PMID 33925464, 2021). "Blocking the CD47-SIRPα pathway with anti-CD47 blocking antibodies increases phagocytosis of tumor cells by macrophages in vitro." (PMID 34572939, 2021). "CD47 is a “Don’t Eat Me” signal that protects healthy cells from macrophage engulfment but is highly expressed on tumor cells, thereby preventing their phagocytosis; it is thus a current target of anti-tumor therapies." (PMID 34097709, 2021). "Research results showed that CD47-SIRPα immune checkpoint pathway played important roles in tumor immune evasion and innate immunotherapy." (PMID 34717705, 2021). "In vivo, treatment of mice with liposomal clodronate, which exhausted macrophages, abolished the tumoricidal effects of CD47-blocking treatments, demonstrating macrophages were essential for robust anti-tumor responses." (PMID 34368156, 2021). "Representing a “don’t eat me” signal, CD47 is overexpressed on the surface of cancer cells in many tumor types." (PMID 34576180, 2021). "The impact of the CD47 blockade on macrophage populations within the tumor microenvironment was also studied." (PMID 34944850, 2021). "It has been widely reported that CD47 was mainly expressed on the surface of circulating hematopoietic stem cells 36, normal erythrocytes 50 and most types of tumor cells." (PMID 34373736, 2021). "The combination of AB21 containing an inactive Fc-domain with rituximab significantly improved anti-tumor activity compared to rituximab alone, consistent with the known impact of CD47–SIRPα antagonism on potentiating responses to antitumor antibody therapy." (PMID 33256806, 2020). "In consistent with the differences of tumor growth rate, the positive ratio of Ki67, a cell division marker, was increased in CD47-overexpressing DLD1 tumors but decreased in CD47-knockdown SW480 tumors compared to their corresponding control groups." (PMID 32226539, 2020). "Improved selectivity of antibodies targeting CD47 expressed on tumor cells should be important for development of successful antibody drugs." (PMID 31931812, 2020). "In summary, CD36 and CD47 have many similarities regarding their role in inflammation, tumor, and angiogenesis." (PMID 32733941, 2020). "Namely, stimulation of the CD47/ signal regulatory protein alpha (SIRPα) axis abolishes phagocytosis of malignant cells and macrophage cytotoxicity against tumor cells." (PMID 32610582, 2020).
tumor (continued). "Anti-CD47 antibody therapy makes not only cancer cells swallowed by macrophages but also anti-tumor cytotoxic T cell immune response initiated." (PMID 33488618, 2020). "Immunotherapy using the anti-CD47 (immune checkpoint inhibitor) treatment has shown promise in treating multiple tumor types, including GBM." (PMID 31547758, 2020). "As a major “don't eat me” signal, CD47 is highly upregulated on the surface of nearly all human tumor cell types, including GBM cells." (PMID 33117364, 2020). "The targeting of this axis with humanized anti-CD47 antibodies enhanced tumour phagocytosis and reduced tumour burden in patient-derived orthotopic xenografts of paediatric brain tumours." (PMID 31973030, 2020). "Targeting CD47 by antibody or other agents can stimulate phagocytosis of tumor cells in many mice models." (PMID 33343560, 2020). "CD47 expression is confirmed on nearly all cancer cells from every primary and xenograft patient tumor sample." (PMID 32411788, 2020). "In our study, lower doses of irradiation and TMZ chemotherapy enhanced anti-CD47-mediated tumor phagocytosis, which is in line with these previous studies." (PMID 31547758, 2020). "Many preclinical studies have shown that abrogation of the SIRPα-CD47 interaction, especially when combined with tumor targeting antibodies or chemo/radiotherapy, promotes cancer cell death and improves survival." (PMID 32240171, 2020). "RQ increased the phagocytic ability of macrophages and decreased the in vitro expression levels of CD47 and SIRPα on tumor cells and macrophages, respectively." (PMID 32020472, 2020). "We prepared a CD47 blockade antibody 2C8 to blockade CD47 on tumor cells with high affinity selectively, and it embodied excellent antitumor capability both in vitro and in vivo." (PMID 33469516, 2020). "The anti-phagocytic signal CD47 is expressed on a wide variety of cancers and acts as an innate immune checkpoint in the tumour microenvironment." (PMID 31205227, 2020). "To date, preclinical studies in mice have shown that CD47-SIRPα myeloid cell-directed checkpoint blockades effectively enhance tumor cell phagocytosis and thus reduce the tumor burden." (PMID 32944390, 2020). "It was found that CD47 expression was markedly higher in various kinds of tumor tissues compared with normal counterparts." (PMID 33020240, 2020). "Recent findings implied the role of cancer cell-expressed CD47 in inhibition of anti-tumor immune responses." (PMID 32610582, 2020). "In this retrospective study, CD47 expression was immunohistochemically examined in tumor biopsies from 169 NSCLC patients." (PMID 32043750, 2020). "Taken together, our study provides a novel anti-CD47 Nb preferentially binding to tumor cells, with potential as a single drug or an ideal module to build BsAb." (PMID 31931812, 2020). "Overexpression of CD47 had been shown to promote tumor invasion and metastasis in non-small cell lung cancer." (PMID 32226539, 2020). "When it binds to its ligand, the signal regulatory protein α (SIRPα) which is an inhibitory receptor on macrophages and dendritic cells, CD47 sends “don’t eat me” signals by inhibiting phagocytosis of tumor cells and triggering an immune evasion." (PMID 32457743, 2020). "In support of this possibility, an improved antitumor response was detected in mice receiving subcutaneous vaccination with anti-CD47-coated B16F10 tumor cells." (PMID 31996683, 2020). "As described in the previous sections, CD47 is overexpressed in a variety of hematological cancers and plays a significant role in tumor evasion of immune surveillance." (PMID 32677994, 2020). "While inhibiting the receptor with the simultaneous administration of anti-CD47 monoclonal antibodies, the phagocytosis and killing capacity of macrophages on tumor cells is significantly increased." (PMID 32161718, 2020). "CD47 is a promising strategy for cancer treatment based on the modulation of both innate and adaptive immune responses to tumor cells." (PMID 32536914, 2020).
tumor (continued). "Hu5F9-G4, a human monoclonal antibody directing against CD47 has been tested in a tumor therapy as a single agent, as well as in combination with cetuximab." (PMID 33251232, 2020). "For this purpose, we used the LSC assay to measure SM antagonism of SIRPα binding to CD47 naturally expressed on tumor cells and compared the activity of these qHTS active SMs to the activity observed in the biochemical assay." (PMID 32240171, 2020). "For instance, one recent study showed that the anti-tumor efficiency of CD47/SIRPα blockades can be reinforced upon combination with CTLA-4, PD-L1 or other ICI blockers." (PMID 32824974, 2020). "suggest that anti-CD47 treatment alone has limited anti-tumor effects and is inefficient in inducing changes within the tumor immune microenvironment or eradicating murine GBMs in immune-competent hosts." (PMID 33329583, 2020). "Tumor cells upregulate CD47, known as the “don't eat me” signal, to escape recognition and clearance by immune cells including macrophages." (PMID 32685002, 2020). "Efforts to disrupt the CD47–SIRPα interaction have mainly focused on targeting CD47 due to its upregulation and ubiquitous expression on most human tumor types." (PMID 33256806, 2020). "Consistently, the tumor growth inhibition efficacy by systemic treatment of pep-20-D12 was similar as the anti-CD47 antibody." (PMID 33020240, 2020). "This can be achieved by conventional standard-of-care chemotherapies to activate ER stress responses that promote tumor cell phagocytosis by professional APCs and combined with CD47 blockade to generate potent T-cell priming and antitumor immune responses." (PMID 32198351, 2020). "The biological effect of CD47 signaling on tumor cell proliferation and metastasis was evaluated in vitro and in vivo." (PMID 32226539, 2020). "CD47 is expressed in all normal cells but overexpressed in tumor cells and it functions as an immune checkpoint in cancer." (PMID 32448366, 2020). "In tumors, CD47 can elevate the expression of macrophages and increase their phagocytosis through IL-6, which affects the clearance of tumor cells and has a great impact on the prognosis of tumor cells." (PMID 32733941, 2020). "The authors found that tumor-localized release of nanobody agonists of CD47 resulted in enhanced proliferation and activation of tumor-infiltrating lymphocytes, leading to durable and systemic antitumor immunity in syngeneic tumor mouse models." (PMID 32206114, 2020). "CD47 is another crucial immune checkpoint protein that is abundantly expressed on the surface of various tumor cells." (PMID 32317755, 2020). "Signal regulatory protein alpha (SIRPα)–CD47 is a classical molecule match to prohibit the phagocytosis of macrophages in tumor immune escape." (PMID 33505964, 2020). "Targeting the CD47–SIRPα axis promotes macrophage migration into the tumor mass, leading to TAMs being functionally switched from a tumor-promoting M2-like phenotype to a tumoricidal M1-like phenotype and enabling TAMs to attack the tumor." (PMID 33469516, 2020). "The IHC scoring of CD8 expression on immune cells and B7-H3 or CD47 on tumor cells was performed by two experienced pathologists who were blinded to the patients’ clinical information." (PMID 32544882, 2020). "MYC is reported to promote tumor cell-intrinsic immune evasion by mediating the overexpression of PD-L1 and CD47 on cancer cells." (PMID 32664564, 2020). "Anti-CD47 mAb treatment was shown to increase in vitro macrophage phagocytosis, to inhibit tumor formation, and to enhance macrophage infiltration in xenograft model of ovarian clear cell adenocarcinoma (SKOV-3)." (PMID 32354198, 2020). "In the tumor and adjacent healthy tissue, significantly higher proportions of CD47-expressing cells were found for both NK cells and CD8+ T cells." (PMID 32811852, 2020).
tumor (continued). "As with most solid tumors and hematological malignancies, blocking the CD47/SIRP-α axis between tumor cells and innate immune cells increases tumor recognition and cell phagocytosis in breast cancer." (PMID 32784928, 2020). "More concretely, 2C8 significantly induces macrophages, including protumorigenic subtype M2 macrophages killing tumor cells in vitro, and is revealed to be more effective than commercially available anti-CD47 mAb B6H12.2." (PMID 33469516, 2020). "Taken together, CD47 is identified as a commonly expressed molecule on cancers, and blockade of its function leads to tumor cell phagocytosis and elimination." (PMID 32314789, 2020). "Expression of different modulators of immune responses such as CD73, CD38, CD24, CD47 and many more can be evaluated on tumor cells, immune cells, or as soluble markers in BAL." (PMID 35582213, 2020). "This CD47 overexpression is co-opted by tumor cells and represents a common feature of hematologic and solid tumors, allowing them to evade innate immune surveillance." (PMID 33117364, 2020). "Accumulating evidence suggests that the blockade of CD47 and its ligands signal regulatory protein α (SIRPα) are promising in tumor immunotherapy." (PMID 32536914, 2020). "Our data indicates that 2C8 increased mouse macrophage-mediated phagocytosis of several types of CD47-positive tumor cells." (PMID 33469516, 2020). "Such delivery resulted in T cell and macrophage induced phagocytosis of tumor cells by blocking CD47 and reduced tumor progression." (PMID 32677994, 2020). "Increased expression of CD47 by tumor cells inhibits their phagocytosis, a crucial way in which they evade immune surveillance." (PMID 32240171, 2020). "In accordance, significant up-regulation of CD47 expression has been reported in CTCs compared to the corresponding tumor tissue in colorectal cancer." (PMID 32041353, 2020). "CD47, a self-recognition protein, is ubiquitously expressed on human cells and upregulated in many different tumour cells." (PMID 33014356, 2020). "Based on the benefits achieved for the treatment of other malignancies, CD47-targeting antibody and human (or murine) SIRPα-Fc have been used to access the anti-tumor effect of GBM by blocking CD47-SIRPα axis in vitro and in vivo." (PMID 32824974, 2020). "Macrophages can be induced to phagocytize tumor cells by CD47/SIRPα-blocking agents, resulting in antigen presentation and promotion of adaptive immune responses against tumors." (PMID 32456204, 2020). "In vitro and in vivo studies showed that blocking CD47-SIRPα interaction by using anti-CD47 mAbs enhanced macrophage-mediated phagocytosis, improved survival, and reduced tumor burden in human GBM engrafted mice." (PMID 31547758, 2020). "Signal regulatory protein α (SIRPα), a transmembrane protein that is predominantly expressed in dendritic cells (DCs) or macrophages, interacts with CD47 that is overexpressed in almost all types of tumor cells." (PMID 32411788, 2020). "Nevertheless, different approaches have also been previously applied to characterize the expression of CD47 or PD-L1 on tumor tissue and CTCs." (PMID 32041353, 2020). "The MC38 line was also insensitive to anti-CD47 treatment, even though the tumor cells did express CD47 at the cell surface." (PMID 33133093, 2020). "CD47 is overexpression in the HCC tumor cells and positively correlates with CD68+ (which is a macrophages marker) expression." (PMID 32466488, 2020). "The application of ICD activation and CD47 blockade strengthened T-cell – mediated reaction, DC maturation tolerance to antitumor, resulting in clinical outcomes, tumor metastasis, and tumor relapse prevention." (PMID 32865029, 2020). "A significant example that CD24, a “Don’t eat me” signal on tumor cells, was found to be complementary to CD47." (PMID 33597922, 2020). "After intervention therapy with anti-CD47 antibody, macrophages can be induced to phagocytose tumor cells." (PMID 33224886, 2020).
tumor (continued). "CD47 is an immune checkpoint protein that downregulates both the innate and adaptive anti-tumor immune response via its counter receptor SIRPα." (PMID 32240171, 2020). "A research pointed out that the main anti-tumor effect of anti-CD47 monoclonal antibodies is attributed to the activation of host cGAS-STING pathway mediated by mitochondrial DNA in DC." (PMID 33488618, 2020). "Studies have confirmed that anti-CD47 antibodies can promote phagocytosis of macrophages on tumor cells through different pathways, including the Fc-dependent mechanism, CD47-SIRPα axis, and direct induction of apoptosis." (PMID 32733941, 2020). "Researches have shown that CD8+ T cells are essential for anti-CD47-mediated tumor regression, and tumor-resident DCs can enhance anti-CD47 by cross-stimulation of antigen-specific T cells." (PMID 33488618, 2020). "CD47 is an antiphagocytic molecule that contributes to tumor cell resistance in host immune surveillance." (PMID 32043750, 2020). "Following these initial reports, CD47 ligation-mediated cell death was confirmed in tumor cells of lymphoid, myeloid, granulocytes, dendritic cells, ovaries, and breasts." (PMID 33224442, 2020). "Recently, CD47 was also reported to be a marker of tumor-initiating cells in various cancer types including HCC, which is responsible for a higher capacity in tumorigenicity, progression and metastasis." (PMID 32544882, 2020). "First, tumor cells in general express CD47 molecule, an inhibitory receptor, which interacts with the signal-regulated protein alpha (SIRPα) on macrophages to prevent phagocytosis of tumor cells by macrophages." (PMID 33396603, 2020). "Some experiments have shown that in GBM, disruption of the SIRPα-CD47 signaling axis is an efficacious method of reeducating TAMs and enhancing tumor cell phagocytosis." (PMID 32944390, 2020). "CD-47 has been disclosed to play an inhibitory role in NK cell-mediated anti-viral or anti-tumor cytotoxicity." (PMID 32117298, 2020). "A significant antitumor protection was also detected in mice that were vaccinated with anti-CD47 antibody-coated tumor or TA-expressing cells." (PMID 31996683, 2020). "The N-terminal V domain of human SIRPα bind human CD47 on tumor cells and prevent it from delivering inhibitory signals to macrophages." (PMID 33329583, 2020). "CD47 is expressed on tumour cells and binds to SIRPα, expressed on myeloid cells, preventing phagocytosis." (PMID 31996683, 2020). "Blocking CD47 also increases the reactivity of anti-tumor T and NK cells and increases the release of various cytokines, including IFN-γ and IL-6." (PMID 32000802, 2020). "Anti-CD47 antibody administration resulted in a dramatically higher proportion of NPC cells phagocytosed by macrophages than did treatment with control IgG, thus confirming that CD47 plays a key role in tumor cell escape from immune surveillance." (PMID 32149101, 2020). "To investigate the distribution of CD47 and PD-L1 on tumor and immune cells within peripheral blood and the tumor microenvironment, we evaluated matched blood and primary and/or metastatic tissue samples from CTC-positive patients." (PMID 32041353, 2020). "Overall, the immunomodulatory effects of MYC oncogene in PDAC mainly happen via increased expression of PD-L1 and CD47 to evade both innate and adaptive immune responses, thus favoring tumor growth." (PMID 32664564, 2020). "Studies have confirmed that IgG inhibition of CD47-SIRPα interaction in vivo and in vitro significantly enhances tumor cell antibody-dependent cell phagocytosis (ADCP) and cytotoxicity (ADCC) and enhances tumor cell neutrophil phagocytosis." (PMID 32733941, 2020). "Previous studies showed enhanced anti-tumor effect with dual targeting of both CD47 and PD-L1 in melanoma and colon carcinoma." (PMID 32677994, 2020). "CD47 is expressed on hematopoietic blood cells; however, tumor cells frequently hijack its expression to escape macrophage scavenging." (PMID 32041353, 2020).